AKT1 (AKT serine/threonine kinase 1)
Diseases named in the same sentence as AKT1 in open-access papers (continued):
Sharing a sentence is not in itself a finding about the gene and the disease.
cancer (continued). "Further investigation showed that phosphorylation of the two Akt isoforms (Akt1 and Akt2) was significantly inhibited by KA39 and KA25 in SW403 and LoVo cancer cells cancer cells." (PMID 33916378, 2021). "One study found that the induction of ROS levels through Nexrutine raised ROS over a certain threshold in cancer cells, leading to the inhibition of growth by impacting the PI3K/AKT1/mTORC1 signaling pathway." (PMID 34831420, 2021). "Previous reports have illustrated that AKT1 regulated EMT progress in human cancers and facilitated EMT progress, which enhanced migratory and invasive capacities of cancer cells." (PMID 32193155, 2020). "Genomic analysis of human cancers has identified that oncogenic events involving classical oncogenes and tumor suppressor genes have a key role in autophagy including PI3K, AKT1, PTEN, proteins of the Bcl-2 family, among others." (PMID 33194736, 2020). "For instance, circNRIP1 was proven to modulate the autophagy and cancer cell metabolism switch into the Warburg effect by alteration of AKT1 expression and, consequently, the AKT/mTOR pathway, which induces tumor development and metastasis in gastric cancer." (PMID 33194736, 2020). "During investigations of the AKT signaling more and more evidence raised that the three isoforms AKT1 (PKBα), AKT2 (PKBβ) and AKT3 (PKBγ) exert distinct and partly even opposing effects in cancer and physiologically." (PMID 31752925, 2019). "For instance, piceatannol suppresses the proliferation of cancer cells by mitochondria-mediated intrinsic pathways, including the PI3K/AKT1/mTOR, spleen tyrosine kinase, cyclooxygenase-2, and IL-6/STAT3 pathways." (PMID 31517069, 2019). "In the cell cycle pathway, GSK3B, CDK2, and CDK1 are reduced by cisplatin in each cell line, and in cancer pathways, cisplatin reduces phosphorylation of GSK3B, AKT1, PDGFRa/b, PLCG1/2, and CDK2." (PMID 31929796, 2019). "Another miRNA, miR-99a, which was downregulated in the diseased sheep, appears to target AKT1 (which has an important role in the PI3K-Akt pathway) and inhibits cancer cell proliferation by targeting mTOR." (PMID 30658565, 2019). "AKT1 and AKT2 play partially redundant roles in many processes of normal and cancer cells, including metabolism, proliferation, cell survival, growth, and angiogenesis." (PMID 31035417, 2019). "In this cascade, both PI3K and mTORC2 are required as upstream regulators for the hypoxia-induced activation of AKT1 and AKT2, which mediate the repression of the viral oncogenes in hypoxic HPV-positive cancer cells." (PMID 30755508, 2019). "Among the cancer driver genes expressed in K-RMS-1 we found increments in the expression of BAX, RASD1, WT1, AKT1, cMYC and NOTCH." (PMID 30745580, 2019). "Our analyses resulted in the identification of an ER-positive HRAS-/PIK3CA-/AKT1-wild type AME harboring an HMGA2-WIF1 fusion gene, which has been described in PAs and carcinomas ex-PA of the salivary gland." (PMID 30675516, 2019). "Peaks involving important cancer genes such as CCND1, EGFR, ERBB2, FGFR1, AKT1, MYC, KRAS and CDKN2A/2B, which were confirmed in our data." (PMID 30131072, 2018). "In summary, we identified differential expression and phosphorylation of AKT1 and AKT2 isoforms in different cancer lineages and genetic backgrounds, including the selective activation by PIK3CA hotspot mutation H1047R of AKT2 but not AKT1." (PMID 30012111, 2018). "MiR-149 is reported to be a pro-apoptotic miRNA, which can inhibit the expression of Akt1 and E2F1 and thus induce cancer cell lines apoptosis." (PMID 30619739, 2018). "Our data revealed that AKT1 and AKT2 isoforms are differentially expressed and, in some cases, differentially phosphorylated in specific cancer lineages and genetic backgrounds." (PMID 30012111, 2018). "As a critical component in the PI3K-AKT signaling pathway, AKT1 was closely correlated with the occurrence and development of human cancers." (PMID 30108661, 2018).
cancer (continued). "Overexpression of α-Klotho or treatment with sKl inhibits insulin/IGF-1-mediated downstream effectors IRS-1, Akt1, and ERK1/2 in cancer cells." (PMID 29250031, 2017). "AZD5363 is an AKT kinase inhibitor that inhibits AKT1, AKT2 and AKT3 that is also in early phase clinical trials in several cancers including PCa." (PMID 28008155, 2017). "The results suggest that csMVP-associated signaling is mediated through the control of ERK1/2, Akt1/2/3, mTOR and FAK signaling pathways, which are critical for cancer growth, survival and metastasis." (PMID 29038587, 2017). "Switching on and off of an array of genes such as BRCA1, BRCA2, Akt1, ERCC1 and ABCB1 were identified to modulate sensitivity toward chemotherapy in cancer patients." (PMID 27980217, 2017). "The link between expression of Akt1-E17K, improved DSB repair, and increased radioresistance highlights a potential use of Akt1-E17K as a biomarker for cancer cell radioresistance." (PMID 28209968, 2017). "In contrast, cancer cell lines classified as the survival phenotype responded well to drugs targeting components of the PI3K pathway, such as Sigma-Aldrich AKT1/2 inhibitor, neratinib, and bafilomycin." (PMID 28446242, 2017). "In accord with previous studies, sOPN induced EMT in cancer; whereas the nuclear OPN triggered MET through the AKT1/miR-429/ZEB axis through interaction with HIF2α." (PMID 28032860, 2016). "Lysine 14-substituted AKT1 shows significantly lower levels of phosphorylation at threonine 308 than wild-type AKT1, and knockdown of SMYD3 as well as treatment with a SMYD3 inhibitor significantly attenuates this phosphorylation in cancer cells." (PMID 27626683, 2016). "AKT1 is involved in cell proliferation and survival, while CAMK2D, a member of the CAMK family, activates cancer cell proliferarion." (PMID 27821810, 2016). "Ad-E1A12–induced AKT1 phosphorylation was PI3K-dependent in epithelial cancer cells, and mTOR-dependent in mesenchymal cancer cells." (PMID 27849011, 2016). "Enzastaurin is believed to execute its anti-cancer activity by inhibiting synthesis of VEGF and/or inhibiting the Akt1 signaling pathway." (PMID 27564101, 2016). "Next, we analyzed the relationships between miR-29b, these four putatively cancer glycolysis-regulating genes, and another key component of the AKT pathway, AKT1." (PMID 26512921, 2015). "Further, the construct utilized by this study activates AKT1, and although it is thought that AKT2 and 3 isoforms can compensate, evidence suggests they play distinct roles in cancer progression." (PMID 25971410, 2015). "Among the three highly homologous AKT isoforms(AKT1, AKT2, and AKT3), most studies have focused on the role of AKT1 in cancer progression." (PMID 26512921, 2015). "Many of these genes, such as AKT1, RUNX1 and LIMA1, are known to be involved in cancer and related processes." (PMID 25884336, 2015). "Top-ranking kinases such as AKT1, CHEK2, and ABL1 regulate core cellular processes of growth and proliferation, and are well-studied cancer drivers according to the CancerGenes database." (PMID 25611800, 2015). "There are three AKT isoforms (AKT1, AKT2, and AKT3) with different expression patterns and functions in several cancer tumors." (PMID 24338765, 2014). "Subsequent work by the team resulted in the development of MK-2206, a drug that shows moderate selectivity for AKT1/2 over AKT3, and is currently in clinical trials for a wide variety of cancers." (PMID 25566081, 2014). "AKT1, another client protein of HSP90AA1, is crucial for survival and proliferation of cancer cells." (PMID 25167922, 2014).
cancer (continued). "There are 3 different protein isoforms, AKT1, AKT2, and AKT3, with overlapping and distinct roles in cancer; for example, AKT1 promotes cellular survival and growth." (PMID 24387695, 2014). "It is worth noting that five of these genes (PIK3CA, HRAS, AKT1, ETV6, and KDM5C) are known to play important roles in cancer and are CGC genes (that is, experimentally validated cancer genes)." (PMID 25360158, 2014). "The cell survival oncoprotein Akt1, also known as protein kinase B (PKB), is frequently hyperactivated in human cancers." (PMID 24658544, 2014). "In support of this notion, both AKT1 and c-MYC synergistically promote metabolic reprograming and aerobic glycolysis in cancer cells." (PMID 24628780, 2014). "We found two major types of complexes that are affected by miRNAs during cancer progression; the first contains SMAD3, SMAD2, SMAD4, SMAD6, FOXO1, HOXC8, and SKIL, which are connected to AKT1, which is in turn a key modulator of TGF-B signaling pathway." (PMID 24391925, 2013). "AKT1 regulates cell survival, and AKT3 plays a critical role in brain development, whereas, AKT2 is more important in cancer development and progression." (PMID 23468863, 2013). "The hubs also include RB1, BCL2, AKT1, CDK2, CASP8 which are involved in mechanisms of apoptosis, to which cells are known to acquire resistance in all types of cancers." (PMID 23166660, 2012). "All three isoforms of AKT, that is AKT1, AKT2, and AKT3, have been reported to be altered in various human cancers." (PMID 22666248, 2012). "Although AKT1, 2, and 3 share high sequence homology, clinical studies suggest the existence of isoform-specific roles of AKT in multiple human cancers." (PMID 22666248, 2012). "Here we report that the induction of cancer cell apoptosis by HDAC inhibitors, such as valproic acid and butyrate, is achieved through inhibition of gene expression of Akt1 and Akt2, pro-survival factors involved in many cell signalling pathways." (PMID 17156483, 2006). "The modulation of pathways involved in cancer metastasis (MMP9), inflammation (PTGS2), cell survival (AKT1), and DNA repair (PARP1) suggests that these compounds could serve as multitargeted therapies, providing an advantage over single-target drugs." (PMID 40283891, 2025). "Besides the ligands, the identified target AKT1 and MAPK are overexpressed in numerous cancer isoforms, along with sharing crosstalk in the cancer signaling pathways." (PMID 40283942, 2025). "Previous studies also indicated that, unlike Akt1 and Akt2 phosphorylation, Akt3 phosphorylation inhibits cancer cell proliferation." (PMID 38499532, 2024). "In addition to the receptors FGFR1, FGFR4 and ERBB4, the main effector AKT1 and its downstream effectors, MTOR, GSK3B, p21, WEE1, BAD and CREB5, which mediate cancer cell growth and progression, also exhibited marked changes in HPV-ind CCs." (PMID 38253702, 2024). "Moreover, an NP study of Yinchen Wuling San, a complex medical prescription comprising six medicinal plants used for cancer treatment, revealed that the genes TNF, AKT1, and EGFR are targeted by the bioactive compounds of Yinchen Wuling San against HNSCC." (PMID 39035991, 2024).
cancer (continued). "Activation of the PI3K/AKT1 pathway is involved in inhibiting the GC development of some anti-cancer substances, including drugs, functional proteins, and non-coding RNAs." (PMID 38283117, 2024). "Interestingly, we discovered that the stable expression of EGFP-K-Ras(V12) resulted in reduced PI3-K p85α as well as Akt1 and Akt2 expression, but increased Akt3 expression in PANC-1 as well as Colo-699 cancer cells." (PMID 38291468, 2024). "Interaction with the mentioned proteins might destabilise AKT1, MDM2, and PRKN signalling pathways, which control cancer cells’ survival, proliferation, invasion, apoptosis, and angiogenesis, making the combined drug’s therapeutic effect promising." (PMID 39204341, 2024). "Prognostic values of AKT1 and AKT3 That a higher expression of AKT3 appears as a marker of bad prognosis is not surprising for a kinase lying in the PI3K-AKT-mTOR pathway so important for cancer cell growth and survival." (PMID 38528080, 2024). "Akt1 (serine-threonine protein kinase) is a part of the PI3K-dependent signaling pathway and is a key cell survival protein functionally involved in antiapoptosis in various cancers." (PMID 39011503, 2024). "AKT1 and AKT2 are crucial for promoting cancer cell survival by conferring resistance to apoptosis." (PMID 39035991, 2024). "In this study, our network pharmacology results showed that AKT1, AKT3, and BCL2 are hub targets, and KEGG pathway enrichment analysis revealed that PI3K-AKT signaling pathway is involved in the effect of Aloin A against cancer-related muscle atrophy." (PMID 38180061, 2023). "Through key components such as Oleanolic acid, Butin, β-sitosterol, Stigmasterol, and Enoxolone and other components interferes with AKT1, IL-6 and TNF, and regulates pathway in cancer, PI3K-AKt signaling pathway and MAPK pathway to play a therapeutic role in hepatitis E." (PMID 37035802, 2023). "Other critical nodes include AKT1, SRC, CTNNB1 and EGFR, which are related to cancer signalling." (PMID 36944690, 2023). "No variants were evident in the key cancer genes PTEN, MTOR, AKT1, TSC1/2 or MDM2, or in genes encoding components of PI3K." (PMID 37079639, 2023). "In addition, we observed the expression dysregulations of NLRX1, AKT1, CSRP1, LEP, MUC4 and SEMA4B in cancer tissues by immunohistochemistry." (PMID 36817485, 2023). "As demonstrated by Rao G, the glycolysis process could be regulated by the PI3K‐modulated AKT1/mTOR axis, thereby accelerating hypoxia‐inducible factor (HIF) activation to enhance angiogenesis and promote glucose uptake in cancer cells." (PMID 37539493, 2023). "For GP5, CDK12 inactivation and gains of AKT1, GSK3B, PIK3CA, CCND1, and MDM2 were identified as the top truncal druggable targets that would be most likely to obtain a durable response due to their presence in all cancer cells." (PMID 37828555, 2023). "The docking results for Akt1 showed that the tested phytochemicals were not as effective as the control anti-cancer drugs LTB and AFT." (PMID 37894581, 2023). "Several kinds of AKT1-, AKT2-, and AKT3-regulating circRNAs are overexpressed in many cancer cells." (PMID 36230902, 2022). "This study suggests that targeting AKT1 in combination with CDK4/6i represents a therapeutic strategy in which cellular senescence can be achieved without the release of pro-cancer factors." (PMID 35158840, 2022). "Unfortunately, further research on the Akt1-miRNA axis in any other cancers was not performed since its first report in 2009." (PMID 35406397, 2022).
cancer (continued). "After further topological analysis by Network Analyzer, we found that NR may play a co-regulatory role on ASD mediated by AKT1, MAPK1, MAPK3 and involve the proteoglycan pathway in cancer, thyroid hormone signaling pathway, ROS pathway, and other pathways." (PMID 36401485, 2022). "TTC3 is a ubiquitin E3 ligase that promotes ubiquitinated degradation and the phosphorylation of Akt, and is related to the regulation of the cancer cell proliferation rate and the tumor heterogeneity mediated by the β1-integrin/FAK/mTORC2/AKT1-related signaling pathway." (PMID 35053609, 2022). "In addition to broadening the scope of AKT1-dependent positive regulation of gene expression, our study unexpectedly discovered that an active AKT1 signaling could also inhibit gene expression—many of which are widely known to be downregulated during cancer progression." (PMID 35892586, 2022). "Moreover, to reduce the ability of inhibiting autophagy, promoting proliferation and EMT by FGF2, and to inhibit the ability of promoting cancer cell metastasis by WNT7A, AKT1 was selected as a biomarker to be inhibited." (PMID 35743172, 2022). "Its role conflicts with other isoforms, such as AKT1, which plays a role in cancer cell proliferation but does not affect metastasis, and AKT3, which plays a more significant part in the progression of triple-negative breast cancer." (PMID 36532641, 2022). "Genetic alterations of the PIK3CA, mTOR, PTEN, AKT1, AKT2, and AKT3 genes in human cancers." (PMID 35402264, 2022). "Due to AKT1/luciferase gene transposition, the HCC clones exhibited bioluminescent reporter gene activity, as well as higher levels of MHC class I protein (H-2Kb) and the cancer stem cell (CSC) marker CD44 compared to Hepa1-6 cells." (PMID 35721518, 2022). "Similarly, AKT1 and HSP90 (HS90A), which are also known SMYD3 targets and are included in Reactome pathways clustering in cancer hallmarks “tumor-promoting inflammation” and “resisting cell death”, respectively, also contain various P-tripeptides." (PMID 35495117, 2022). "Capivasertib was previously shown to inhibit all three isoforms of AKT (AKT1, AKT2 and AKT3) in enzyme assays and reduce phosphorylation of its downstream substrates P70S6K or PRAS40 and in vitro growth of a subset of various cancer cell lines and xenografts." (PMID 34066040, 2021). "This study suggests that the mechanism of the C. maackii flower against cancer might strengthen anti-inflammatory responses by inactivating the PI3K-Akt signaling pathway, bound to Urs-12-en-24-oic acid, 3-oxo-, methyl ester on Akt1." (PMID 34641448, 2021). "As AKT1 is often overactivated in cancer cells and as this should result in increased NMD efficiency, the possibility that this increase might affect cancer processes and be targeted in cancer therapy is discussed." (PMID 34634811, 2021). "The anti-cancer effect of THSWD might by achieved via the down-regulation of MAPK1, HRAS, GRB2, AKT1, and MAPK14." (PMID 34513708, 2021). "AKT, is a serine/threonine protein kinase comprising three isoforms—namely: AKT1, AKT2 and AKT3, whose inhibitors have been recognized as promising therapeutic targets for various human disorders, especially cancer." (PMID 33920446, 2021). "There were more FLT3, FGFR1, and AKT1 mutations (p-value < 0.05) in nonhypermutated cancers, while there were more RET, CBL, and DDR2 mutations (p-value < 0.05) in hypermutated cancers." (PMID 34503126, 2021). "AKT1 is one of the AKT kinases, involved in many biological processes such as proliferation, cell survival growth, and angiogenesis, and the therapeutic potential of inhibitors targeting PI3K-AKT pathway in cancer has been discussed." (PMID 34381520, 2021).